MIR4436B1 (microRNA 4436b-1)
Synonyms: hsa-mir-4436b; MIR4436B; hsa-mir-4436b-1
Gene: MicroRNA gene on chromosome 2 (110,086,433 to 110,086,523, reverse strand). Ensembl gene ENSG00000264979.
Homologues: Paralogues in human: MIR4436B2 (100% identical).